VDR (vitamin D receptor)
Diseases named in the same sentence as VDR in open-access papers (continued):
Sharing a sentence is not in itself a finding about the gene and the disease.
migraine (continued). "Since neurogenic inflammation is an essential part of migraine pathogenesis, further studies are indeed advisable to establish whether the interplay between VDR agonists and VDR gene polymorphisms may have a role in preventing the development or worsening of migraine attacks." (PMID 24900990, 2014). "The finding on the possible influence of the VDR rs731236 SNV in triggering migraine attacks by ethanol deserves further studies." (PMID 37553799, 2023). "The possible relationship between VDR rs731236 and the triggering of migraine episodes with ethanol deserves future studies." (PMID 37553799, 2023). "The frequency distribution analysis of the VDR haplotypes in migraine patients versus the control group and MwoA patients versus controls did not reveal any significant associations." (PMID 37755360, 2023). "We genotyped 290 patients diagnosed with migraine and 300 age‐matched controls using specific TaqMan assays for VDR rs2228570, VDR rs731236, VDR rs7975232, VDR rs739837, VDR rs78783628, GC rs7041, and GC rs4588 SNVs." (PMID 37553799, 2023). "The frequencies of VDR rs731236 (A/A) and VDR rs731236 (G/G) genotypes were, respectively, significantly higher and significantly lower in patients in which alcohol was a triggering factor for migraine attacks." (PMID 37553799, 2023). "When analyzing each sex separately migraine women showed a lower frequency of the VDR rs731236 (A/G) genotype, which disappeared after correction for multiple comparisons as well." (PMID 37553799, 2023). "Serum vitamin D receptor levels have been found to be decreased, and serum vitamin D‐binding protein levels are similar in migraine patients compared with controls in a single study." (PMID 37553799, 2023). "In addition, we studied other common SNVs in the VDR and GC genes in Caucasian Spanish patients diagnosed with migraine and in healthy controls." (PMID 37553799, 2023). "In summary, the results of the current study suggest a lack of association between common SNVs in the VDR and GC gene and the risk of developing migraine." (PMID 37553799, 2023). "Age at onset of migraine according to the VDR and GC genotypes." (PMID 37553799, 2023). "VDR and GC genotypes of patients with migraine and healthy controls." (PMID 37553799, 2023). "Mean ± SD age at onset of migraine attacks was significantly lower in patients carrying the VDR rs731236 (G/G) genotype compared with those carrying the VDR rs731236 (A/G) genotype and in those carrying the GC rs7041 (A/C) compared with GC rs7041 (A/A) genotype." (PMID 37553799, 2023). "Since VDR has a central role in exerting the majority of 1,25(OH)2D biological responses, and it occurs in various CNS regions, VDR could represent a candidate gene for migraine." (PMID 37755360, 2023). "It has been proposed that VDR and the 1-hydroxylase may contribute to the triggering of chronic headaches and migraines." (PMID 36000140, 2022). "Our results were obtained from a small sample size and included only migraine patients without aura; therefore this is a preliminary conclusion and provides little evidence for a causal association between migraine and VDR polymorphisms." (PMID 23984350, 2013). "In addition, serum VDR levels were found to be lower in migraine patients compared to controls." (PMID 37755360, 2023). "In addition, subgroup analyses revealed a significant association between all three studied VDR variants, particularly with a migraine without aura subtype." (PMID 37755360, 2023). "The implication of VDR genetic variants in migraine pathogenesis has not been previously investigated in the Southeastern European population residing in Greece, although a study in an Iranian population provided evidence for an association between VDR polymorphisms and migraine susceptibility." (PMID 37755360, 2023). "The TaqI and FokI VDR polymorphisms were associated with migraine without aura." (PMID 34945279, 2021).
migraine (continued). "The aim of this study was to find whether there is an association between two VDR polymorphisms (TaqI and FokI) and migraine without aura." (PMID 23984350, 2013). "Therefore, the current study provides supporting evidence for a possible association of VDR variants with migraines, particularly migraine without aura susceptibility in Southeastern Europeans residing in Greece, further reinforcing the emerging role of vitamin D and its receptor in migraines." (PMID 37755360, 2023).
pancreatitis (11 papers, 2016 to 2025). Inflammation of the pancreas. "Firstly, the sample size of each group was too small and therefore insufficient to elucidate the association between the severity of pancreatitis and the level of VDR expression." (PMID 37808100, 2023). "Further studies are needed to confirm the underlying anti-inflammatory mechanisms of VD/VDR signaling in pancreatitis." (PMID 35631254, 2022). "It is unknown whether the VDR present in endocrine islets could affect inflammatory cells to cause pancreatitis because research on its effect on inflammation has usually been limited to in vitro studies." (PMID 37808100, 2023). "Moreover, vitamin D could be used to prevent adverse effects caused by VDR reduction in canine pancreatitis." (PMID 37808100, 2023). "VDR-directed therapy offers a dual advantage by decreasing fibrosis and inflammation in both acute and chronic murine pancreatitis." (PMID 40620673, 2025). "For example, VDR ligands (e.g., calcipotriol) suppress pancreatitis and VDR acts as a master transcriptional regulator in pancreatic stellate cells." (PMID 35406694, 2022). "Further studies that investigate the effect of vitamin D supplementation on VDR are needed to clarify whether vitamin D metabolism modification can ameliorate pancreatitis in dogs." (PMID 37808100, 2023). "The present study demonstrated that VDR expression is decreased in canine pancreatitis and suggests that VDR could be a potential target to treat pancreatitis in dogs." (PMID 37808100, 2023). "VDR expressed in stroma from human pancreatic tumors and calcipotriol could reduce markers of inflammation and fibrosis in pancreatitis and human tumor stroma, suggesting vitamin D priming as an adjunct in the treatment of pancreatic ductal adenocarcinoma." (PMID 35406694, 2022). "Here, we added new insights into the putative role of SNPs in VDR in pancreatitis development, and, therefore, this study contributes to individualized research on the interaction and impact of environmental factors, including nutrition, in pancreatic secretory disorders." (PMID 29966312, 2018). "Although the circulating levels of 1,25(OH)2D in dogs with pancreatitis were not determined, a decreased 25(OH)D concentration was reported in dogs with pancreatitis and might have negatively regulated VDR transcription in inflamed pancreases." (PMID 37808100, 2023). "Single nucleotide polymorphisms (SNPs), Apa-1, Bsm-1, Fok-1, and Taq-1, in the vitamin D receptor gene (VDR) are known in various diseases, but not yet in pancreatitis." (PMID 29966312, 2018).
vitamin D-resistant rickets (11 papers, 2013 to 2026). "Mutations resulting in the VDR becoming unresponsive or less responsive to its substrate include hereditary vitamin D resistant rickets (vitamin D dependent rickets type 2) and result in hypocalcaemia and early onset rickets." (PMID 32942601, 2020). "We analyzed the transcriptomic response to 1,25D in fibroblasts bearing a severe homozygous hereditary vitamin D resistant rickets-related p.Arg30* VDR mutation (MUT) and in control fibroblasts (CO)." (PMID 30959822, 2019). "VDR mutations lead to hereditary vitamin D-resistant rickets (HVDRR), an autosomal recessive disorder characterized by early-onset hypocalcemic rickets typically accompanied by alopecia; in general, mutations in the DBD lead to more pronounced phenotypes." (PMID 30959822, 2019). "The functional study of different mutations on vitamin D receptor (VDR) gene causing hereditary vitamin D-resistant rickets (HVDRR) remains limited." (PMID 29127362, 2017). "The importance of the cutaneous VDR is demonstrated in certain human patients with hereditary vitamin D-resistant rickets and mice that harbor loss-of-function mutations in the VDR and eventually develop hair loss (alopecia totalis), as well as impaired skin wound repair." (PMID 27898044, 2016). "Vitamin D dependent rickets type II or hereditary vitamin D resistant rickets (HVDRR) is characterized by impaired recognition of 1,25(OH)2D due to a mutation of the vitamin D receptor (VDR)." (PMID 36292765, 2022). "This second type involves a defective vitamin D receptor (VDR), resulting in vitamin D resistant rickets (VDRR), also known as VDDR type 2A (VDDR2A)." (PMID 30282619, 2019). "Individuals with a non-functional VDR suffer from the absence of VDR signaling giving rise to the disease hereditary vitamin D resistant rickets (HVDRR)." (PMID 23785369, 2013).
allergic asthma (10 papers, 2009 to 2024). A asthma with a basis in a pathological type I hypersensitivity reaction. "Similarly, VDR knockout would inhibit the symptoms of another Th2-mediated disease, experimental allergic asthma, confirming the protective role of VDR deficiency in Th2-cell direct diseases." (PMID 32541827, 2020). "Controversially, it has also been described that less Th2-cytokines IL-4, -5, and -13 are produced by VDR-KO Th2 cells, and vitamin D can inhibit the allergic asthma phenotype." (PMID 29593729, 2018). "The authors also noted that in a mouse study, the VDR-deficient mice failed to develop experimental allergic asthma, and this suggested that vitamin D play a key role in the generation of Th2-driven inflammation in lung diseases." (PMID 34702190, 2021). "VDR-deficient mice failed to develop experimental allergic asthma, leading the authors to suggest a role for vitamin D in driving Th2 inflammation in the airways[69 ▶]." (PMID 32429643, 2020). "Furthermore, VDR-KO mice have an impaired resistance to allergic asthma, supporting the notion of a suppressive effect of VDR absence on Th2 responses." (PMID 29593729, 2018). "This pathway has until now been unexplored in pulmonary fibrosis, however it is important to note that VDR-deficient mice failed to develop experimental allergic asthma, suggesting an important role for the vitamin D endocrine system in the generation of Th2-driven inflammation in the lung." (PMID 19347046, 2009). "In addition, VDR KO mice on either the Balb/c or C57BL/6 background failed to develop experimental allergic asthma." (PMID 25912039, 2015).
autoimmune hepatitis (10 papers, 2013 to 2023). Hepatitis caused by autoantibodies. "Among a variety of VDR gene polymorphisms, BsmI and TaqI have been reported to be associated with autoimmune liver diseases." (PMID 24171052, 2013). "VDR polymorphisms have been investigated in the context of some chronic liver diseases, such as primary biliary cirrhosis and autoimmune hepatitis." (PMID 23586065, 2013). "VDR also plays a role in immune cell differentiation and proliferation, and some VDR polymorphisms have been associated with primary biliary cholangitis and autoimmune hepatitis." (PMID 36012285, 2022). "The aim of the study was to characterize the relationship between polymorphisms of the vitamin D receptor (VDR) gene and the quality of life in patients with autoimmune hepatitis (AIH) and primary biliary cholangitis (PBC)." (PMID 32727130, 2020). "In autoimmune hepatitis (AIH), some of the VDR and CTLA4 variants are involved in triggering the immune process, these genotype variants being linked with fatty acid synthase (FAS) promoter variants or pro-inflammatory cytokines that are part of the TNF superfamily." (PMID 36077185, 2022).
cholestasis (10 papers, 2012 to 2023). Impairment of the bile flow caused by obstruction within the liver, or outside the liver in the bile duct system. "“Classical” targeting of VDR through vitamin D substitution improves bone density in patients where cholestasis leads to chronic vitamin D deficiency and increased rates of osteoporosis." (PMID 23540496, 2013). "Lithocholic acid, a biliary compound that accumulates in cholestasis, can activate VDR and alter vitamin D signaling." (PMID 36142636, 2022). "In this study, we examined the effects of VDR deletion in a mouse model of cholestasis and found that VDR-null mice show increased plasma bilirubin levels and reduced intestinal Il6 induction after BDL compared to wild-type mice." (PMID 23240054, 2012). "In this study, we investigated the in vivo role of VDR in the setting of cholestasis using VDR-null mice." (PMID 23240054, 2012). "To examine the effect of VDR deletion on cholestasis, we performed BDL and sham surgery on wild-type mice and VDR-null mice." (PMID 23240054, 2012). "Together, the reduced activation of FXR, LXR, PXR and VDR could be responsible for reduced adaptive responses to the effects of the cholestatic drugs and lead to development of cholestasis." (PMID 27344345, 2017). "Moreover, signaling pathways such as FXR, LXR, PXR and VDR, which play a prominent role in cholestasis, are also significantly affected." (PMID 27344345, 2017). "In human cholestasis, elevated VDR may up-regulate levels of bile acids transporters (e.g. MRP3), but not induce detoxification enzymes (e.g. SULT2A1)." (PMID 25798860, 2015). "Because impaired absorption of fat-soluble vitamins is a hallmark of cholestasis and severe liver dysfunction, low serum vitamin D levels are commonly observed in patients with cholestasis and may alter VDR activity with consequences beyond bone metabolism." (PMID 23540496, 2013). "We examined the effect of VDR deletion in a mouse model of cholestasis." (PMID 23240054, 2012). "One of the most important roles of VDR is to inhibit CYP7A1 mRNA expression and bile acid synthesis, thereby protecting hepatocytes against cholestasis." (PMID 36142636, 2022). "Our research combined with previous studies proved that VDR and YAP1 was extremely downregulated in cholestasis and both VDR–/– mice and YAP1–/– mice were more sensitive to cholestasis-induced liver injury." (PMID 32296329, 2020). "To investigate the mechanism underlying the amelioration of EE-induced hepatotoxicity and cholestasis after baicalin treatment, we focused on hepatic nuclear receptors: FXR, CAR, PXR, and VDR that are closely related to BA homeostasis." (PMID 32116682, 2019). "Calcipotriol supplement revised the YAP1 downregulation in cholestasis but did not effect the expression of VDR." (PMID 32296329, 2020). "Meantime, the protein level of VDR detected by western blot was downregulated in DDC-induced cholestasis and calcipotriol supplement did not revise this downregulation." (PMID 32296329, 2020). "Calcipotriol may work to counteract metabolic inflammation via activating VDR and overexpession of YAP1 to suppress the excessive activation of NLRP3 inflammasome in cholestasis." (PMID 32296329, 2020). "Although the use of vitamin D or synthetic VDR agonist as disease-modifying agents represents an attractive therapeutic concept for cholestatic liver diseases, especially when vitamin D levels are already low because of cholestasis, data from controlled studies are lacking." (PMID 23540496, 2013).
chronic hepatitis C (10 papers, 2013 to 2025). "Low VDR protein expression has also been associated with severe necroinflammatory activity and severe fibrosis in patients with genotype 1 chronic hepatitis C." (PMID 37511164, 2023). "Previous studies showed that genetic variation of the vitamin D metabolic pathway, including CYP27B1-1260 rs10877012 and VDR FokI rs2228570, was associated with sustained virological response to PegIFN therapy in patients with chronic hepatitis C infection." (PMID 28296915, 2017). "VDR gene polymorphisms are independently related to the response to Peg-IFN+RBV therapy in chronic hepatitis C and could be used as complementary biomarkers of response when included in a prediction algorithm in association with demographic, virologic, biochemical and genetic traits." (PMID 24073221, 2013). "In patients with chronic hepatitis C, portal vein inflammation is significantly higher in patients with VDR-negative inflammatory cells and low VDR expression in hepatocytes." (PMID 37511164, 2023). "Frequencies of the VDR genotypes and the bAt haplotype in Thai patients with chronic hepatitis C infection treated with PEG-IFN." (PMID 31565578, 2019). "This study reveals that a common nonsynonymous SNP in the VDR gene (rs2228570 T/C), which is studied here for the first time in chronic hepatitis C patients, is a predictor of the clinical outcome of combined interferon plus ribavirin therapy." (PMID 24073221, 2013). "We conclude that two polymorphic sites in the VDR gene that influence the response rate to interferon-ribavirin therapy in chronic hepatitis C exist." (PMID 24073221, 2013). "Several genetic polymorphisms associated with 25 (OH) vitamin D signaling and metabolism have been studied in patients with chronic hepatitis C. The Vitamin D receptor (VDR) contains several and among them a combined genotype, in strong linkage disequilibrium, referred to as CCA haplotype." (PMID 32822420, 2020). "HCV could down-regulate VDR, which was similar to a previous study that low VDR expression was observed in hepatocytes of chronic hepatitis C subjects." (PMID 29385741, 2018). "Hepatocyte expression of VDR was induced in non-alcoholic fatty liver disease (NAFLD) and decreased in non-alcoholic steatohepatitis (NASH) or chronic hepatitis C." (PMID 35505652, 2022). "Logistic regression analysis of demographic, biochemical and virological variables at baseline and of CYP27B1, VDR and IL28B gene polymorphisms in relation with the lack of response (failure to antiviral therapy) in 238 patients with chronic hepatitis C." (PMID 24073221, 2013).
diabetic retinopathy (10 papers, 2016 to 2025). "In a Chinese cohort, the F allele of the VDR FokI polymorphism was linked to decreased diabetic retinopathy risk." (PMID 41438090, 2025). "Vitamin D receptor (VDR) genotypes have been associated with the cumulative prevalence of diabetic retinopathy." (PMID 26885530, 2016). "Furthermore, while HWE deviations can impact the interpretation of genetic associations, our findings still provide valuable insights into the relationship between VDR TaqI polymorphism and diabetic retinopathy risk." (PMID 40264687, 2025). "In diabetic retinopathy, studies have focused on VDR gene polymorphisms and disease susceptibility." (PMID 41438090, 2025). "The mechanism underlying the role of VDR ApaI A > C and BsmI C > T variants in diabetic retinopathy remains unclear." (PMID 36143273, 2022). "The Bsm1 gene polymorphism of vitamin D receptor is known to be related with diabetic retinopathy." (PMID 29320437, 2018). "What is more, proof of the VDR polymorphisms related with diabetic retinopathy was found." (PMID 28335514, 2017). "The vitamin D receptor (VDR) is another ligand-binding nuclear receptor with therapeutic relevance to the progression of angiogenesis in diabetic retinopathy." (PMID 32326149, 2020).